DICER1 (dicer 1, ribonuclease III)
Diseases named in the same sentence as DICER1 in open-access papers (continued):
Sharing a sentence is not in itself a finding about the gene and the disease.
infection (16 papers, 2010 to 2025). The state of being infected such as from the introduction of a foreign agent such as serum, vaccine, antigenic substance or organism. "Another example is that infection with Kaposi’s sarcoma-associated herpesvirus (KSHV) resulted in increased expression of DICER1 mRNA in primary human umbilical vein endothelial cells, whereas mRNA expression levels of DGCR8, DROSHA, and XPO5 did not change significantly." (PMID 37243263, 2023). "Does the mechanism by which GP63 in Lm-CM targets DICER1/miR-122/hepcidin axis to deplete Nramp1 levels in cultured macrophage cells also operates under actual infection conditions?" (PMID 41135672, 2025). "Our in vitro and in vivo animal infection experiments collectively reveal that by depleting DICER1/miR-122, GP63 drives hepcidin upregulation in macrophages, leading to proteasomal degradation of Nramp1." (PMID 41135672, 2025). "In agreement, our data also revealed that GP63 expression was abundant at 12 h p.i. but declined sharply by 72 h, supporting the conclusion that GP63 primarily exerts its effect on DICER1 during the early phase of infection." (PMID 41135672, 2025). "For example, increased expressions of Ago1 and Dicer1 were detected upon slow bee paralysis virus (SBPV) infection in bumblebees and linked to 17 differentially expressed miRNAs upon infection." (PMID 38098491, 2023). "Knockdown of VSV-GFP was also obtained in the mouse MSC cell line that contains functional Dicer1 when pre-soaked with long dsRNA containing N protein sequence for 2h prior to infection." (PMID 35603190, 2022). "Compared with lentivirus-C treated controls, relative levels of Emx2-mRNA upon OS1-179(+) infection, changed by a factor of 0.56/1 = 0.56 (p<0.001) - and 1.42/1.65 = 0.87 (p<0.01), in wild type and Dicer1-KD NIH/3T3 cells, respectively." (PMID 20066053, 2010). "To determine whether this observation also holds true during infection, we next examined DICER1 levels in L. major-infected macrophages at different time points post-infection (6–72 h p,i)." (PMID 41135672, 2025). "We speculate that co-option of the B2_Mm2 element as an enhancer of Dicer1 facilitates upregulation of Dicer1 in response to conditions that drive TE upregulation, such as infection or stress." (PMID 37158599, 2023). "In addition, Dicer1, Dicer2, Drosha, and Ago1 are involved in miRNA biogenesis and increased polysome loading after infection in mosquitoes." (PMID 29718912, 2018). "In agreement with our in vitro data, we observed a significant reduction in the DICER1 levels with a concomitant surge of hepcidin levels in the footpad sections of the mice infected with LmWT or LmCas9/T7 strains at 6- and 13-weeks post infection compared to uninfected mice." (PMID 41135672, 2025). "During infection with L. donovani gp63 cleaves Dicer1, that could impact in post-transcriptional regulation of host-mRNAs by miRNA/RNP interactions, as showed by Dicer1-mediated inhibiting of pre-miR-122 processing and downregulation of miR-122 activity in Huh7 cells." (PMID 28276497, 2017). "The three cell types were infected with the SARS-CoV-2 delta variant at an MOI of 0.1, and mRNA expression levels of AGO2, DICER1, DGCR8, DROSHA, and XPO5 were measured 24 h and 48 h after infection." (PMID 37243263, 2023). "A significant increase in mRNA levels of AGO2, DICER1, DGCR8, and XPO (all p-values= 0.03) was found 24 h after infection." (PMID 37243263, 2023). "On the other hand, infection of Vero E6 cells with SARS-CoV-2 impacted mRNA levels of AGO2, DICER1, DGCR8, and XPO5 at 24 h." (PMID 37243263, 2023). "mRNA level changes of DICER1, DGCR8, and XPO were approximately 2-fold, and of AGO2 approximately 4.6-fold, 24 h after infection." (PMID 37243263, 2023). "However, in Vero E6 cells, AGO2, DICER1, DGCR8, and XPO5 mRNA levels were slightly upregulated 24 h after infection with SARS-CoV-2." (PMID 37243263, 2023).
infection (continued). "Further studies are required to determine whether key interactions of PACT with RNAi pathway components, such as TRBP or DICER1, are not disrupted by the compounds, and that RNAi pathway functionality is indeed restored by the compounds during infection." (PMID 37834238, 2023). "The results showed that infection of NHBE and Calu-3 cells with SARS-CoV-2 did not impact mRNA expression levels of AGO2, DICER1, DGCR8, DROSHA, and XPO5 at 24 and 48 h post infection, in good concordance with our results on patient samples." (PMID 37243263, 2023).
adenocarcinoma (5 papers, 2008 to 2025). A common cancer characterized by the presence of malignant glandular cells. "Most low-grade fetal adenocarcinoma/well-differentiated fetal adenocarcinoma (WDFA) of the lung shows nuclear expression of β-catenin and CTNNB1 somatic mutations, but the coexistence of mutations in CTNNB1 and DICER1 is uncommon." (PMID 40892116, 2025). "However, in adenocarcinoma cell lines displaying hypomorphic DICER1 phenotype, of 97 known miRs, only 55 were differentially expressed." (PMID 19578509, 2008).
CNS tumors (5 papers, 2022 to 2025). "This review sought to investigate the presence and characteristics of DICER1 mutations in rare CNS tumors and to discuss their potential implications for early recognition of DICER1-related syndromes." (PMID 40361440, 2025). "Studies suggest that DICER1 mutations in different domains may play distinct roles in the oncogenesis of various primary CNS tumors." (PMID 40361440, 2025). "A primitive CNS tumor, especially with rhabdomyoblastic and/or chondroid differentiation, should prompt DICER1 testing." (PMID 34599283, 2022).
gynecological tumors (4 papers, 2021 to 2025). "In this work, we describe young patients with constitutive biallelic deactivation of the XPC gene developing gynecological tumors with somatic DICER1 mutations." (PMID 37567969, 2023). "Larger sample sizes will be needed to better understand the role and specificity of DICER1 mutations for XP gynecological tumors." (PMID 37567969, 2023). "In this work, we demonstrated increased mutagenesis, specific mutation signature and common DICER1 alterations in gynecological tumors of XP-C patients." (PMID 37567969, 2023).
neurodegenerative disease (4 papers, 2012 to 2025). A disorder of the central nervous system characterized by gradual and progressive loss of neural tissue and neurologic function. "Emerging evidence suggests that polymorphism(s) in these genes (DICER1 and DROSHA) may alter the biological functions of miRNAs and contribute to the pathogenesis of various systemic and neurodegenerative diseases." (PMID 37099569, 2023). "Notably, it might promote neurodegenerative disease and adversely affect the nervous system compared with Dicer1 wild-type AD mice (Wilcoxon rank-sum test, p < 0.05), although the prediction needs to be validated." (PMID 40926280, 2025).
benign tumors (3 papers, 2014 to 2016). "Little is known about the pathogenesis of ovarian SLCT however, germ-line mutations in the microRNA processing gene DICER1 have been shown to be related with the development of benign tumors that are susceptible to malignant transformation." (PMID 27473538, 2016).
hematologic malignancies (2 papers, 2024 to 2025). "Consistent with previous reports of their association with poor prognosis in solid tumors, our findings extend the relevance of DICER1 and DROSHA alterations to hematologic malignancies as well." (PMID 41463093, 2025).
metabolic disease (2 papers, 2019 to 2020). A congenital disorder (due to inherited enzyme abnormality) or acquired (due to failure of a metabolically important organ) disorder resulting from an abnormal metabolic process. "Mutations in DICER1 gene and reduced Dicer activity are associated with increased susceptibility to stress, apoptosis, developmental abnormalities, aging, metabolic disorders, disturbed immune system and neuronal functions, and neurodegeneration." (PMID 33240194, 2020).
proliferative retinopathy (2 papers, 2016 to 2020). "Therefore, the age-related loss of DICER1 can contribute to retinal disorders by affecting not only RPE cells, but also HRECs." (PMID 32765950, 2020). "The observed decrease in miRNA expression was in line with the decreased expression DICER1 and the corresponding increase in that of Alu RNA, supporting the general conclusion for the involvement of Alu RNA excess in retinal disorders induced by DICER1 impairment." (PMID 32765950, 2020).
cardiovascular diseases (1 paper, 2015). "The involvement of DICER1 and the miRNA pathway in PTSD is consistent with the overall psychosomatic picture of PTSD reported by these epidemiological studies, since both DICER1 and miRNAs have been implicated in cardiovascular diseases." (PMID 26632874, 2015).
neurodevelopmental disorder (1 paper, 2022). A behavioral and cognitive disorder with onset during the developmental period that involves impaired or aberrant development of intellectual, motor, or social functions. "Instead, we identified several rare, likely pathogenic variants in seven genes implicated in neurodevelopmental disorders: KLHL17, TDO2, TRRAP, EIF3F, ATP10A, DICER1, and CDH15." (PMID 35743796, 2022).
psychiatric disorder (1 paper, 2015). A disorder characterized by behavioral and/or psychological abnormalities, often accompanied by physical symptoms. "Studies are needed to elucidate the relationship between blood and brain DICER1 and miRNA regulation as well as mechanisms underlying the connection between blood DICER1 and miRNA regulation and stress-related psychiatric disorders to contribute to their prevention and treatment efforts." (PMID 26632874, 2015).
DICER1 also shares sentences with these, for which no sentence is quoted: viral infection (8 papers); cutaneous melanoma (4); mesenchymal hamartoma (4); anaplastic thyroid carcinoma (3); Blindness (3); central nervous system sarcoma (3); dilated cardiomyopathy (3); genetic disorder (3); gestational hypertension (3); hereditary cancer (3); juvenile granulosa cell tumor (3); lymph node metastasis (3); adrenocortical adenoma (2); adrenocortical tumors (2); Ataxia (2); Azoospermia (2); B cell lymphoma (2); childhood cancer (2); colon adenocarcinoma (2); Ewing sarcoma (2); Fanconi anaemia (2); gastrointestinal polyp (2); HIV-1 infection (2); Hyperglycemia (2); kidney (2); leukopenia (2); liver cancer (2); Lynch syndrome (2); Macrocephaly (2); meningioma (2).
A further 144 diseases each share a sentence with DICER1 in 2 papers or fewer.